CREBBP (CREB binding lysine acetyltransferase )
Diseases named in the same sentence as CREBBP in open-access papers (continued):
Sharing a sentence is not in itself a finding about the gene and the disease.
lymphoma (continued). "For example, CREBBP mutation, which occurs in about 60% of FL, has been associated with reduced expression of antigen presentation machinery, impaired immune surveillance, and inferior outcome as compared with CREBBP WT lymphoma patients." (PMID 34267181, 2021). "Protein kinase Cβ (PRKCB) plays a role in autophagy regulation, CREBBP inactivation promotes the development of HDAC3-dependent lymphomas, and abnormal expression of Casein kinase 2α1 (CSNK2A1) is linked to neurological diseases and cancer." (PMID 34211501, 2021). "recently showed that HDAC3-selective inhibitors have a dual effect by reversing CREBBP-mutant aberrant epigenetic programming limiting lymphoma growth inhibition while restoring antitumor immunity, notably antigen presenting-genes." (PMID 34335584, 2021). "A similar association between CREBBP inactivation and reduced expression of MHC class II is observed in murine lymphoma models which alters mutant GC cells ability to present antigen to CD4+ cells." (PMID 34335584, 2021). "Without jumping to conclusions, it would be interesting to know if mutations that result in decreased or lost KMT2D expression in GC B-cells also result in decreased CREBBP/P300 recruitment to and activation of enhancers in GC B-cells and/or lymphoma." (PMID 33277464, 2020). "For instance, deleterious and/or loss of function mutations in the histone acetyltransferase CREB binding protein (CREBBP) or the E1A binding protein 300 (EP330) have been reported in about 40% of DLBCL and FL patients as well as in other lymphoma subtypes." (PMID 31681423, 2019). "cAMP response element binding protein (CREB) binding protein (CREBBP) mutant GC lymphomas have reduced MHC class II expression through epigenetic silencing by HDAC3." (PMID 31261914, 2019). "CREBBP, one of the most frequently mutated genes in DLBCL, acts as a tumor repressor of GC-derived pathogenesis of lymphoma." (PMID 31366566, 2019). "HDAC3 selective inhibitors are of interest for precision therapy of patients with CREBBP‐mutant lymphomas." (PMID 30874354, 2019). "It was found that FL patients with a single missense mutation in the KAT domain of the CREBBP gene experienced an extremely low number of early adverse events related to lymphoma and had better long-term survival rates, regardless of treatment option." (PMID 40725159, 2025). "Histone deacetylase 3 (HDAC3) is recruited by the transcription repressor BCL6 to form a deacetylation complex with SMRT and NCoR to counteract the activity of CREBBP for gene enhancer regulation, which maintains the unopposed deacetylation state in CREBBP-mutant lymphoma." (PMID 39117798, 2024). "Mutations in CREBBP (20%) and EZH2 (13%) were common in all progression cases of GCB COO, and lymphomas harboring alterations in these epigenetic modifiers may respond to histone deacetylase inhibitors and enhancer of EZH2 inhibitors, respectively." (PMID 39392347, 2024). "Moreover, CREBBP mutant lymphoma cells were also more sensitive to HDAC3i in a cell autonomous manner, which has led to the concept of using these drugs for precision therapy in FL and DLBCL." (PMID 38570506, 2024). "Ultimately, our findings could facilitate the clinical development of predictive and/or response biomarkers for the rational use of HDAC3-targeting agents in lymphoma, especially the CREBBP wild-type cases." (PMID 39117798, 2024). "Particularly this HDAC3 involvement is of potential therapeutic interest, as subtype-specific HDAC inhibitors are currently being developed and could potentially be used to treat CREBBP-mutant lymphomas." (PMID 38124747, 2023).
lymphoma (continued). "Notably, the enhancers and genes dysregulated in tumors with aberrant TET2 are the same as those repressed in CREBBP-mutant lymphoma." (PMID 35237302, 2022). "We propose that lack of intrafollicular CD4 + T cells can be considered as a surrogate biomarker of immune escape in a manner analogous to the case of CREBBP mutant lymphomas, which indeed benefit from HDAC3-selective inhibitors to promote immune-related activities." (PMID 34267181, 2021). "Conditional knock-out alleles have been successfully employed to study the in vivo role of many lymphoma-associated tumor suppressor genes encoding for transcription factors (BLIMP1), epigenetic modifiers (EZH2, CREBBP, KMT2D, TET2), small G proteins (GNA13) and ubiquitin ligases (FBXO11)." (PMID 34456919, 2021). "Interestingly, CREBBP-mutated lymphoma B cells maintained this dependency toward EP300 enzymatic activity which identify a unique vulnerability that provide exciting opportunities of targeting single mutant CREBBP or EP300 GC-derived lymphomas." (PMID 34335584, 2021). "Future studies could evaluate the possibility that CREBBP loss and STAT6 gain, possibly through BCL-xL, are sufficient to induce dFL-like lymphomas." (PMID 32555149, 2020). "CREBBP inactivation expedites GC-derived pathogenesis of lymphoma." (PMID 31366566, 2019). "Mutation in this complex in lymphoma has been described, showing that about 39% of DLBCL and 41% of follicular lymphoma patients have genomic deletions and/or somatic mutations that inactivate or remove the acetyltransferase domain of EP300 and CREBBP." (PMID 28725161, 2017). "We next examined whether CREBBP and KMT2D deficiency altered the lymphoma immune microenvironment." (PMID 38570506, 2024). "Perhaps not surprisingly, TET2 and CREBBP mutations are mutually exclusive in human lymphomas." (PMID 38124747, 2023). "When CREBBP was removed in lymphoid committed progenitors (CD19-driven model), lymphoma occurred only occasionally and was much less aggressive." (PMID 38440231, 2024). "Epigenetic alterations in lymphoma include those involved in DNA methylation (e.g. DNMT1), histone acetylation (e.g. CREBBP), histone methylation (e.g. EZH2) and non-coding RNA (e.g. miR-155)." (PMID 37869076, 2023). "Crebbp deletion coupled to myc ectopic expression in mice leads to earlier lymphoma development in mice, while xenografts from mutant CREBBP human DLBCL cells expand faster and to a greater extent than tumours of wild-type CREBBP human DLBCL." (PMID 35580618, 2022). "As a consequence, CREBBP mutant FLs featured lower infiltration of CD4+ T cells and were impaired in activating autologous T cells as compared to CREBBP wild type (WT) lymphoma ex vivo." (PMID 35237302, 2022). "In validation of these findings, known CREBBP/EP300 dependent cancer types (i.e., PCa, lymphoma, myeloma, and leukemia) all ranked highly for CREBBP/EP300 dependency versus other cancer types." (PMID 34199844, 2021). "We report that the bromodomains of the histone acetyltransferases CREBBP/EP300 are critical to sustain the proliferation of human leukemia and lymphoma cell lines." (PMID 29884215, 2018). "Here, we explore the antiproliferative properties of CREBBP/EP300 bromodomain inhibition in leukemia and lymphoma cell lines and explore the molecular mechanisms responsible for such effects, using both chemical and genetic approaches." (PMID 29884215, 2018). "Deletion of CREBBP down-regulates the transcription of MHC class II genes, which contributes to the immune evasion of malignant lymphoma cells." (PMID 28152507, 2017). "Furthermore, combined inactivation of CREBBP/KMT2D was shown to specifically trigger CD8pos T cell exclusion from malignant follicles in both human and murine lymphomas." (PMID 38022603, 2023). "Interestingly, CREBBP-mutant lymphomas become dependent to HDAC3, the histone deacetylase opposing the effect of CREBBP, that has been identified as a relevant therapeutic target in these tumors." (PMID 34335584, 2021).
lymphoma (continued). "Comparing with historical control (NCT01852435), the 2-year PFS and OS rates of double-expressor lymphoma phenotype (DEL) were improved, and negative prognostic effect of histone acetyltransferases CREBBP/EP300 mutations was also mitigated by CR-CHOP." (PMID 33097085, 2020). "In our study, we included KMT2D, CREBBP, EZH2, EP300, MEF2B, and TET2 in our lymphoma panel." (PMID 31403034, 2019). "CREBBP, KMT2D, and EZH2 are thus frequent epigenetic hits, initially considered as direct tumor inducers regulating B-cell proliferation and differentiation, but now widely recognized for their additional role as modulators of lymphoma TME, in particular based on the data obtained in GEMM." (PMID 38022603, 2023).
Rubinstein-Taybi syndrome (57 papers, 2006 to 2026). "The bioinformatic analysis specifically focused on the EP300 and CREBBP genes, which are commonly implicated in Rubinstein-Taybi syndrome (MIM #613684)." (PMID 40692712, 2025). "The loss of function variant of CREBBP is causative for Rubinstein-Taybi syndrome (OMIM# 180849) or Menke-Hennekam syndrome 1(OMIM# 618332)." (PMID 35761346, 2022). "Mutations in CREBBP have been found in patients with Rubinstein Taybi syndrome and acute lymphoid leukemia." (PMID 36114448, 2022). "CREBBP is the gene mutated in Rubinstein-Taybi syndrome, an autosomal dominant syndrome characterized by intellectual disability and increased risk of benign tumor formation, including meningiomas." (PMID 36514795, 2022). "Further, patients with Rubinstein-Taybi syndrome have an increased risk of developing medulloblastoma, and CREBBP mutations have been found in sporadic medulloblastoma." (PMID 34373489, 2021). "Rubinstein-Taybi syndrome (RSTS) is a rare neurodevelopmental disorder caused by mutations in CREBBP or EP300 genes encoding CBP/p300 lysine acetyltransferases." (PMID 34071322, 2021). "In fact, EP300, together with its paralogous CREBBP, is a gene whose variants are causative of Rubinstein Taybi syndrome by a mechanism of haploinsufficiency." (PMID 33337535, 2021). "Mutations in the gene encoding CREBBP can lead to Rubinstein-Taybi syndrome (RTS), so there is some overlap in the clinical manifestations of FHS and RTS." (PMID 34805044, 2021). "Mutations in CREBBP lead to Rubinstein-Taybi Syndrome (RTS), which is characterized by intellectual disability (ID) but not autism per se." (PMID 26730956, 2016). "Mutations in the histone acetyltransferase CREB binding protein (CBP, CREBBP) cause Rubinstein-Taybi Syndrome (RTS), a developmental disorder that includes ASD-like symptoms." (PMID 26730956, 2016). "Seizure disorder was reported to be more frequent in Rubinstein-Taybi syndrome patients with CREBBP mutations." (PMID 24959624, 2014). "It interacts with CREBBP, a master transcriptional regulator (and the cause of the developmental disorder Rubinstein-Taybi syndrome, when mutated)." (PMID 25329894, 2014). "Heterozygous mutation of CREBBP causes Rubinstein-Taybi syndrome, of which the core symptom is intellectual disability (MIM ID# 180849)." (PMID 23227143, 2012). "Rubinstein-Taybi syndrome can be caused by a mutation in the gene which codes for CREB binding protein (CREBBP)." (PMID 23190929, 2012). "Patient 4821 has a 78 Kb deletion within the first exon and upstream sequence of the CREB binding protein (CREBBP), haploinsufficiency of which causes the Rubinstein-Taybi syndrome." (PMID 21439053, 2011). "The patient is an 8 year-old boy whose clinical features are characteristic of the Rubinstein-Taybi syndrome, which has been associated with deletions and other mutations of CREBBP in other patients." (PMID 19917086, 2009). "While CREBBP variants in exons 30–31 have been associated with Rubinstein-Taybi syndrome, the CBP TAZ2 domain spanning amino acid residues 1772–1840 is a functionally distinct region, as variants within TAZ2 are now consistently linked with MKHK and a specific DNA methylation signature." (PMID 40860344, 2025). "CREBBP is one of pathogenic genes of Rubinstein-Taybi syndrome." (PMID 30770747, 2019). "Numerous studies have proved that CREBBP could influence the susceptibility of cancers, Rubinstein-Taybi syndrome and diabetes." (PMID 30326835, 2018). "In addition, there is an apparent high incidence of preeclampsia in women carrying a child with a mutation in CREBBP/EP300 (Rubinstein-Taybi Syndrome)." (PMID 26171964, 2015). "In addition, mutations and deletions of CREBBP causes the Rubinstein-Taybi syndrome which is characterized by MR." (PMID 19557186, 2009). "Variants elsewhere in CREBBP and EP300 result in Rubinstein-Taybi syndrome (RSTS1, OMIM # 180849 and RSTS2, OMIM# 613684), which is largely phenotypically distinct." (PMID 40860344, 2025).
Rubinstein-Taybi syndrome (continued). "Here we report a patient with initial diagnosis of Rubinstein-Taybi syndrome (RSTS, OMIM #180849, #613684), another chromatinopathy which causative genes CREBBP or EP300 encode for two HATs." (PMID 38753158, 2024). "Partial or complete deletion of the CREBBP gene was reported to be responsible for Rubinstein-Taybi syndrome, which is characterized by intellectual disability, postnatal growth deficiency, microcephaly and distinctive facial features." (PMID 31312255, 2019). "There are two types of Rubinstein-Taybi syndrome (RSTS): Type 1, which is caused by mutations of the CREBBP gene; and Type 2, which is caused by mutations of the EP300 gene." (PMID 30635043, 2019). "Heterozygous mutations in CREBBP and, to a lesser extent, EP300 cause Rubinstein-Taybi Syndrome (RTS), a congenital condition mainly characterized by mental retardation, distinctive facial features, and broad toes and thumbs." (PMID 26730956, 2016). "These include single-gene exonic deletions in NRXN1, GRM8, CREBBP (Rubinstein-Taybi syndrome, MIM:180849), KDM4B, and DMD." (PMID 27257017, 2016). "Many of these disorders also present with a recognizable facial gestalt and include some of the classic dysmorphic syndromes, such as Kabuki syndrome (e.g., KMT2D; MIM: 147920 and MIM: 602113) or Rubinstein-Taybi syndrome (e.g., CREBBP; MIM: 180849 and MIM: 600140)." (PMID 41468891, 2026). "Interestingly, truncated CBP protein (gene CREBBP) leads to classical Rubinstein-Taybi syndrome phenotypes in mice characterized by atrial and ventricular septal defects." (PMID 19245720, 2009). "Mutations in CREBBP and EP300 are causative for Rubinstein-Taybi syndrome (RSTS, OMIM 180849 and 613684)." (PMID 26171964, 2015). "The ATN1 gene located on 12p interacts with CREBBP, a master transcriptional regulator, mutations in which are known to cause Rubinstein Taybi syndrome, no obvious change was noticed in the expression level of CREBBP in the probands' tissue studied (skin fibroblast)." (PMID 25329894, 2014). "In others, such as Alagille syndrome (deletion of 20p12; OMIM 118450) or Rubinstein-Taybi syndrome (deletion of 16p13.3; OMIM 180849), haploinsufficiencies of a single gene (Jagged1 (JAG1) or CREBBP, respectively) accounts for all the characteristic features." (PMID 21857958, 2011). "As a congenital multisystemic disorder sharing some similar clinical features with CdLS, Rubinstein-Taybi syndrome (RSTS;OMIM180849,613,684) arises from dysfunction in cyclic-AMP-regulated enhancer binding protein (CREBBP) and E1A binding protein p300 (EP300) as transcriptional co-activators." (PMID 30770747, 2019). "Rubinstein-Taybi syndrome (RSTS) is characterized by distinctive facial features, broad and often angulated thumbs and halluces, short stature, and moderate-to-severe intellectual disability, classified into two types RSTS1 (CREBBP-RSTS) and RSTS2 (EP300-RSTS)." (PMID 37085840, 2023).
breast cancer (43 papers, 2009 to 2025). A primary or metastatic malignant neoplasm involving the breast. "A chromatin-remodeling gene CREBBP was found to be overexpressed in breast cancers, and is frequently mutated in bladder cancers." (PMID 32293263, 2020). "Distinct cancers rely on unique regulatory circuits: for instance, HCC frequently engages SIRT1–p62 or PCAF–microtubule pathways, whereas breast cancer emphasizes p300/CREBBP-driven stabilization of transcription factors (e.g., HOXB13, RB1CC1)." (PMID 41213956, 2025). "In breast cancer, CREBBP acetylates RB1CC1 at K276, preventing its ubiquitination and degradation, thereby stabilizing RB1CC1, enhancing autophagy, and promoting resistance under stress conditions." (PMID 41213956, 2025). "For the non-cancer adipose-breast network that we applied to the breast cancer GWAS, Downstreamer prioritised seven known breast cancer driver genes among the top 100 genes: CREBBP, TRPS1, ARID1A, ARID1B, XBP1, SPEN and NUMA1." (PMID 39010058, 2024). "We then treated BT-549 and MDA-MB-231 breast cancer cell lines with C646, a CREBBP inhibitor, and found that the protein level of NUCB2 decreased in a dose-dependent manner with increasing concentrations of C646." (PMID 37277807, 2023). "Oncoprint analysis revealed genetic alterations in FABP4 (14%), ADIPOQ (2.9%), PPARG (2.8%), PPARGC1A (1.5%), CD36 (1.7%), and CREBBP (11%) in patients with breast cancer in a TCGA study." (PMID 36114448, 2022). "This work provides a mechanistic rationale for the exploration of CREBBP/EP300 acetyltransferase inhibition as a therapeutic strategy in ER+ breast cancer." (PMID 35353838, 2022). "To investigate the anti-tumor effects of CREBBP/EP300 HAT inhibition in ER+ breast cancer in vivo, we used an MCF7 xenograft model." (PMID 35353838, 2022). "To better understand how CREBBP/EP300 HAT inhibition leads to transcriptional changes in ER+ breast cancer cells, we performed ATAC-seq and H3K27 acetyl ChIP-seq upon treatment of MCF7 cells with CPI-1612." (PMID 35353838, 2022). "We noted that GI50 values for CPI-1612 were similar for ER positive breast cancer cell lines in both culture conditions, demonstrating that CREBBP/EP300 inhibition can directly impact hormone-driven proliferation." (PMID 35353838, 2022). "Oncoprint analysis showed genetic alterations in FABP4 (14%), ADIPOQ (2.9%), PPARG (2.8%), PPARGC1A (1.5%), CD36 (1.7%), and CREBBP (11%) in patients with breast cancer in a TCGA study." (PMID 36114448, 2022). "CREBBP/EP300 HAT inhibition suppresses EGR-dependent transcription in breast cancer in vitro and in vivo." (PMID 35804935, 2022). "Oncoprint analysis revealed genetic alterations in FABP4 (14%), ADIPOQ (2.9%), PPARG (2.8%), PPARGC1A (1.5%), CD36 (1.7%), and CREBBP (11%) in patients with breast cancer in the TCGA study." (PMID 36114448, 2022). "DNA methylation analysis revealed that the predictive significance of FABP4, ADIPOQ, PPARG, PPARGC1A, CD36, and CREBBP in a specific CpG was significant in the emergence of breast cancer." (PMID 36114448, 2022). "We demonstrated a heatmap and prognostic value of DNA methylation clustering of the expression levels of FABP4, ADIPOQ, PPARG, PPARGC1A, CD36, and CREBBP in breast cancer." (PMID 36114448, 2022). "LINC01857 is thought to promote breast cancer progression by regulating CREB1 activation via interacting with CREBBP." (PMID 34458145, 2021). "Specific genes, such as PTEN, protein kinase A (PKA), GSK3B, CREBBP, SPEN have been linked to CSC biology and metastasis in breast cancer." (PMID 33167919, 2020). "It should be noted that some genes highly related with breast cancer rank at top but are missed by the NCG4.0 such as the CREBBP, RHOA, HDAC1, ATM and MYC." (PMID 31088372, 2019).